GRM1 (glutamate metabotropic receptor 1)
Diseases named in the same sentence as GRM1 in open-access papers (continued):
Sharing a sentence is not in itself a finding about the gene and the disease.
melanoma (continued). "A neuronal receptor, metabotropic glutamate receptor 1 (GRM1), when ectopically expressed in melanocytes, induces in vitro melanocytic transformation and spontaneous malignant melanoma development in vivo in a transgenic mouse model." (PMID 29416686, 2018). "Previous studies reported that the aberrant expression of GRM1 induced spontaneous melanoma development in vivo." (PMID 30124166, 2018). "Subsequent studies identified Grm1 expression in 80% of human melanoma cell lines and 65% of primary to secondary metastatic melanoma biopsies, but no Grm1 was detected in normal melanocytes or benign nevi." (PMID 29464040, 2018). "Subsequent studies revealed GRM1 RNA and protein overexpression in 80% of human melanoma cell lines and 65% of human melanoma biopsy samples." (PMID 29416686, 2018). "Previously, we have shown that ectopic expression of Grm1 alone in melanocytes was sufficient to induce spontaneous melanoma development with 100% penetrance in transgenic mouse models." (PMID 29464040, 2018). "Our laboratory previously showed that ectopic expression of Grm1 is sufficient to induce spontaneous melanoma formation with 100% penetrance in transgenic mouse model, TG-3, which harbors wild-type BRaf." (PMID 29464040, 2018). "The human relevance of these results was revealed not only in melanoma, but also in breast and renal cell carcinoma, suggesting that Grm1 is a player in numerous malignancies." (PMID 29464040, 2018). "Our lab previously showed that ectopic expression of metabotropic glutamate receptor 1 (Grm1) is sufficient to induce spontaneous melanoma formation with 100% penetrance in a transgenic mouse model." (PMID 29464040, 2018). "Consistent with this, exposure to GRM1 antagonists led to reduced melanoma cell growth in vitro and tumorigenicity in vivo." (PMID 29416686, 2018). "Our laboratory showed that a gain-of-function of murine GRM1, when ectopically expressed in melanocytes, induced in vitro melanocytic transformation and spontaneous malignant melanoma development in vivo in transgenic mouse models with 100% penetrance." (PMID 29416686, 2018). "All melanoma cell lines tested are GRM1-positive but they each have differential xCT expression levels." (PMID 30425240, 2018). "In this analysis SelenBP1 was found to be one of the strongest down-regulated gene of a total of 1,085 down-regulated genes in Tg(Grm1) melanoma samples compared with nevi tissue." (PMID 29535818, 2018). "Stable Grm1-expressing mouse melanocytic clones, MASS clones, were established to elucidate the mechanism underlying Grm1-mediated signaling pathways in melanoma." (PMID 29464040, 2018). "In this study, the role of metabotropic glutamate receptor 1 (GRM1) in the production and release of exosomes in melanoma cells was explored." (PMID 29416686, 2018). "GRM1 was first recognized for its oncogenic potential after a transgenic mouse model presented with spontaneous melanomas." (PMID 28591718, 2017). "Examples of metabotropic glutamate receptors being implicated in development of cancers are the involvement of GRM1 and GRM5 in the induction of melanoma in transgenic mice." (PMID 26730743, 2016). "We demonstrated that ectopic expression of metabotropic glutamate receptor 1 (GRM1) in melanocytes was sufficient to induce spontaneous melanoma development in vivo and transformation in vitro." (PMID 27941674, 2016). "Similar findings by the Pavan laboratory demonstrate that SOX10 haploinsufficiency prevents melanoma formation in a Grm1-transgenic mouse melanoma model." (PMID 25670789, 2015). "Addition of micromolar concentrations of Riluzole, a putative glutamate receptor antagonist (GRM1) enhanced Wnt/β-catenin signaling, shown to decrease proliferation and increase the differentiation of melanoma cells in vitro when combined with exogenous Wnt3a." (PMID 25915038, 2015). "Insertional mutagenesis of Grm1 or melanocyte-specific overexpression of Grm1 or Grm5 leads to melanoma in transgenic mouse models." (PMID 25326682, 2014).
melanoma (continued). "High-throughput genomic studies have identified GRM1, GRM3, GRM4, GRM8 and GRIN2A as susceptibility genes in non-small-cell lung cancer (NSCLC), melanoma, osteosarcoma, and bladder cancer." (PMID 25326682, 2014). "The role of GRM1 in melanomagenesis has been subsequently elucidated, while melanoma growth suppression occurs with its targeted inhibition." (PMID 23922822, 2013). "Insertional mutagenesis resulting in disruption in intron 3 of GRM1 induced its expression and unexpectedly produced melanomas with 100% penetrance in a mouse model." (PMID 23922822, 2013). "Systemic delivery of the U1 adaptors targeting BCL2 and GRM1 suppresses tumor growth in melanoma xenografts by up to 60–70%." (PMID 24285958, 2013). "Recently, in an important proof-of-concept study, the U1 adaptor approach was shown to be highly effective in suppression of melanoma growth in xenografts models, by targeting metabotropic glutamate receptor 1 (GRM1) and B-cell lymphoma 2 (BCL2) transcripts." (PMID 24285958, 2013). "As the role of GRM1 continues to be elucidated in melanoma, less is known about its role in breast cancer." (PMID 23922822, 2013). "Here, we analyzed spontaneously occurring immune responses during melanoma development in grm1-transgenic LLA-TG-3 mice." (PMID 22674057, 2012). "A link between grm1 overexpression and the development of hereditary melanoma was demonstrated by the targeted expression of murine grm1 cDNA under a melanocyte-specific promotor (dopachrome tautomerase; DCT)." (PMID 22674057, 2012). "This group also found that riluzole did not induce a decrease in ERK phosphorylation in the A375 melanoma cell line, in contrast to the decrease in phosphorylated ERK in all human melanoma cell lines positive for GRM1." (PMID 23077590, 2012). "In conclusion, we report here that both cellular as well as cytokine-dependent immunosuppressive mechanisms are employed during melanoma development in grm1-transgenic LLA-TG-3 mice." (PMID 22674057, 2012). "This was done by introducing exogenous dominant negative GRM1 constructs in human melanoma cell lines that resulted in a reduction in melanoma cell growth." (PMID 24619402, 2010). "In the current review, we will discuss how the identification of the oncogenic properties of GRM1 opens up new strategies for the design of potential novel therapies for the treatment of melanoma." (PMID 24619402, 2010). "In order to definitively demonstrate that GRM1 has a direct etiological role in melanoma development in our model system, we generated a new transgenic line using wild-type mouse Grm1 cDNA under a melanocyte-specific promoter, dopachrome tautomerase (Dct)." (PMID 24619402, 2010). "Our group showed in a transgenic mouse model system that ectopic expression of Grm1 in melanocytes is sufficient to induce spontaneous melanoma development in vivo." (PMID 24619402, 2010). "In melanoma, GRM1 has been identified as a significant driver of tumor growth and progression." (PMID 41424711, 2025). "A connection between CYLD expression and the onset of melanoma was demonstrated with Tg(Grm1)EPv." (PMID 38672652, 2024). "Notably, the loss of only one Sox10 allele is sufficient to counteract the activity of oncogenes, such as Nras and Grm1, and to prevent melanoma in transgenic murine melanoma models." (PMID 39092608, 2024). "We used tumor tissue derived from the tails of Tg(Grm1)EPv mice, a melanoma mouse model derived from C57BL/6 mice that carries a metabotropic glutamate receptor 1 (Grm1) transgene under the control of the dopachrome tautomerase promoter, resulting in melanocyte-specific overexpression." (PMID 36831408, 2023). "Melanoma cells of Tg(Grm1)Cyld−/− mice also demonstrate changes in chromatin structure." (PMID 37387450, 2023).
melanoma (continued). "A total of 6 patients had evaluable tissue for IHC analysis of GRM1, 4 of which (patient 23 with sarcoma, patient 33 with acinar cell pancreas, patients 2 and 26 with melanoma) showed statistically significant (p < 0.05) decrease in GRM1 expression from pre- to post-treatment tissue." (PMID 37036756, 2023). "GRM1 inhibitors as therapies for melanoma are currently in clinical trials." (PMID 36137995, 2022). "Bosserhoff and colleagues showed that a homozygous loss of CYLD led to a shortened latency in melanoma development and progression in our Grm1-driven spontaneous melanoma mouse model Tg(Grm1)EPv, as well as increased vasculogenic mimicry and lymph angiogenesis." (PMID 36139432, 2022). "In contrast to Grm1, Grm5 is normally expressed in both normal melanocytes and melanoma tumors." (PMID 35158973, 2022). "The possibility that GRM1/mGluR1 may be uniquely qualified to serve as a viable target for melanoma therapies was assessed in vitro and in vivo with riluzole (Rilutek®), an FDA-approved treatment for Amyotrophic Lateral Sclerosis (ALS)." (PMID 36139432, 2022). "In addition to NRSF/NRSE interaction and epigenetic regulation, the Sp1 transcriptional activator was also found to be involved in the regulation of GRM1 in human melanoma cells." (PMID 36139432, 2022). "Our lab is currently evaluating the therapeutic effects of troriluzole plus anti-PD-1 in our Grm1 driven spontaneous melanoma prone mouse model, this combinatorial approach is also under clinical investigation in melanoma patients with brain metastases (NCT04899921)." (PMID 34359771, 2021). "Tg(Grm1)/Cyld−/− mice autochthonously developed melanoma mainly on the tail and ears, due to an increased expression of the metabotropic glutamate receptor 1 (GRM1) under the control of the melanocyte specific Dct (Trp-2) promoter, and a lack of the tumor suppressor cylindromatosis (CYLD)." (PMID 34830742, 2021). "Finally, we wanted to translate this into the transgenic melanoma model and investigated the survival of tg(Grm1)EPv with spontaneous tumors after therapy cessation and we observed that the combination treatment prolonged survival." (PMID 33408092, 2021). "Additionally, we have derived a spontaneous Grm1 expressing amelanotic melanoma prone mouse model, LLA and a hairless spontaneous Grm1 expressing melanoma prone mouse model, TGS." (PMID 34359771, 2021). "Heterozygous mice which harbor only one copy of the disrupted Grm1 gene shows very similar onset and progression of melanoma to the homozygous mice but raised lesions occur at a much later time and they succumb to high tumor burden by ten to twelve months of age." (PMID 34359771, 2021). "To investigate if the T cells are able to mediate antitumor immunity, we injected transplantable B16.OVA melanoma cells at week 4 of treatment into the flank skin of tg(Grm1)EPv mice and terminated treatment at week five according to the original treatment scheme." (PMID 33408092, 2021). "Here, we show that qRT-PCR-based analysis of Trp-1 transcription can also be used to quantify low pulmonary metastatic burden in the Tg(Grm1)/Cyld−/− autochthonous melanoma model, extending the range of metastasis models for which qRT-PCR-based strategies can be used." (PMID 34830742, 2021). "HIF-1α could also be activated by the PI3K/AKT/mTOR signaling pathway, which is upregulated in numerous cancers including GRM1-expressing melanoma cells." (PMID 32937954, 2020). "Our spontaneous melanoma-prone mouse model is driven by the ectopic expression of a normal neuronal receptor, Metabotropic Glutamate Receptor 1 (protein: mGluR1; gene: GRM1) in melanocytes which is a useful model to study spontaneous metastasis in a biologically and physiologically relevant manner." (PMID 33614507, 2020). "Additionally, influence of metabotropic glutamate receptor 1 (GRM1) expressed on melanoma cells was tested for cell migration and invasiveness." (PMID 32709086, 2020).
melanoma (continued). "Additionally, the Grm1 mRNA expression in lymph node tissues of Tg(Grm1) Cyld+/+ and Tg(Grm1) Cyld−/− mice was analyzed as marker for melanoma cell dissemination." (PMID 31591386, 2019). "We next examined whether U87MG glioma cells secrete glutamate into the extracellular environment as we have demonstrated for GRM1+ melanoma cells." (PMID 31073373, 2019). "Thus, our results confirm the Tg(Grm1) mouse model as a reliable model for further investigations regarding molecular processes in malignant melanoma." (PMID 31591386, 2019). "The generated Tg(Grm1) Cyld+/+ and Tg(Grm1) Cyld−/− mice were then analyzed for melanoma onset." (PMID 31591386, 2019). "Taken altogether, the results of our current study suggest that expression of mutated BRafV600E can induce Grm1 expression in melanocytes, but is not sufficient to induce spontaneous melanoma formation." (PMID 29464040, 2018). "The result was supported by the finding that RNA-sequencing analysis of the Tg(Grm1) mouse model uncovered also no melanoma-associated mutations or single nucleotide variations." (PMID 29535818, 2018). "To evaluate the importance of SELENOK for progression of melanoma in vivo, we utilized a spontaneous melanoma transgenic (Tg) mouse model involving overexpression of the glutamate receptor 1 (Grm1) under control of the melanocyte specific tyrosine-related protein 2 (Trp2) promoter." (PMID 29568366, 2018). "In summary, our results show that data obtained from the Tg(Grm1) mouse model are relevant to the human system and may provide insights into molecular modifications leading to melanoma development and progression." (PMID 29535818, 2018). "This association between GRM1 and the aggressiveness of the exosomes released by cells expressing GRM1 may provide hints to elucidate the aggressive nature of GRM1-expressing melanomas, and the role of exosomes in their metastatic potential." (PMID 29416686, 2018). "We postulate that Grm1 may be an intermediate signaling molecule in BRAFV600E expressing melanomas that contributes to melanomagenesis." (PMID 29464040, 2018). "In this study, we sought to determine whether exosome formation might play a role in GRM1 mediated melanoma development and progression." (PMID 29416686, 2018). "Furthermore, Tg(Grm1) mice offer the possibility to compare nevi and melanoma tissue from the same genetic background with respect to changes in the gene expression profile." (PMID 29535818, 2018). "Additionally, levels of elevated glutamate, the natural ligand of GRM1, were found only in GRM1-expressing melanoma cells, suggesting the establishment of an autocrine loop." (PMID 29416686, 2018). "Transgenic Tg(Grm1) mice serve as a murine model system for spontaneous melanoma development and provide some benefits compared with other melanoma models, avoiding the complication of using and having the feature of metastasis to distant organs including lung and liver." (PMID 29535818, 2018). "In contrast, if ectopic expression of Grm1 is turned on first, then regardless of wild-type or mutated BRaf in the melanocytes melanoma development is the consequence." (PMID 29464040, 2018). "Riluzole has been shown to indirectly inhibit GRM1 activity in melanoma." (PMID 28591718, 2017). "Additionally, combined riluzole and ionizing radiation treatment in GRM1-expressing melanoma cell lines and melanoma xenografts in mice yielded synergistic suppression of cell growth and tumor progression as compared to radiation alone." (PMID 28591718, 2017). "In neostriatal neurons, GRM1 activation by binding of a group I mGluR agonist results in activation of casein kinase 1 (CK1), a highly conserved serine-threonine kinase which was recently implicated as a tumor suppressor in melanoma." (PMID 23922822, 2013).
melanoma (continued). "Aberrant expression of GRM1, a transmembrane domain G protein-coupled receptor that mediates glutamate signaling, plays a crucial role in the onset of melanoma in mouse models, and dysregulated glutamatergic signaling leads to transformation and tumorigenesis in multiple cancer types." (PMID 24285958, 2013). "GRM1 modulation also affects in vivo tumorigenesis of melanoma, prostate and renal cancer cells." (PMID 23922822, 2013). "Furthermore, siRNA knockdown of GRM1 in human melanoma cell also resulted in a decrease in AKT2 phosphorylation corroborating that AKT2 is a downstream target of GRM1." (PMID 23372575, 2012). "In order to test whether such models indeed reflect the human situation and could thus be suitable to study immunotherapies preclinically, we scrutinized spontaneous immune responses against melanoma in the grm1-transgenic mouse model LLA-TG-3." (PMID 22674057, 2012). "The observation that melanoma cell lines released high levels of glutamate, resulting in a glutamate-based autocrine activation of GRM1, prompted our group to consider riluzole as a potential therapeutic agent acting through the inhibition of glutamate release from melanoma cells." (PMID 23077590, 2012). "We have established the etiological role of GRM1 in melanoma." (PMID 24619402, 2010). "One difference could be that the C8161 human melanoma cells were established from a metastatic tumor while the MASS cells we used in the current study were derived from in vitro selection of transformed cells after transfection with Grm1 cDNA." (PMID 38732030, 2024). "Similar to human melanoma, our transgenic mouse models showed consistent metastases to various organs, suggesting Grm1-mediated melanocytic transformation may be a relevant model to investigate the function-suppressive potential of L1 antagonists in cell migration in vitro and in vivo." (PMID 38732030, 2024). "Interestingly, GRM1 up-regulation is also present in human melanoma cell lines and tissues." (PMID 29535818, 2018). "Consequently, activation of ectopically expressed GRM1 initiates signaling cascades important for melanoma pathogenesis, which could include activation of the exosomal production pathway, paving the way for metastasis." (PMID 27092178, 2016). "In addition, in the UACC930 melanoma cell line, where the expression of GRM1 protein is not detectable, the induction of Smad2 and Smad3 linker phosphorylation in the presence of riluzole is comparable to that of the other melanoma cell lines that express GRM1." (PMID 23077590, 2012). "In addition, the aberrant expression of GRM1 in approximately 65% of melanoma biopsies and cell lines reinforced the hypothesis that GRM1 could become a therapeutic target in melanoma therapy." (PMID 23077590, 2012). "Horizontal transfer of proteins such as glutamate metabotropic receptor 1 (GRM1) carried by EVs from GRM1-positive cells promoted migration, invasion, and anchorage-independent growth of melanoma GRM1-negative cells." (PMID 36674479, 2023). "GRM1 activation induces downstream MAPK and PI3K-AKT-mTOR signaling, pathways known to be aberrantly activated in multiple cancers, particularly melanoma." (PMID 37036756, 2023). "Works from the laboratory of S. Chen showed that GRM1 expression results from activation of the MAPK and PI3K/AKT pathways, the main pathways activated in melanoma." (PMID 35158973, 2022). "Of the eight GPCRs shown to be involved in pigmentation, only three have been studied in the context of melanoma (EDNRB, MC1R, and GRM1)." (PMID 35158973, 2022). "The Bosserhoff group used our Grm1-driven mouse model, TG(Grm1)Epv, to elucidate the function of the tumor suppressor gene, deubiquitinase cylindromatosis (CYLD), in melanoma development and progression." (PMID 34359771, 2021). "CYLD −/− TG(Grm1)Epv mice showed early melanoma onset and tumor progression compared to CYLD +/+ TG(Grm1)Epv mice." (PMID 34359771, 2021).